BRCA1 (BRCA1 DNA repair associated)
Diseases named in the same sentence as BRCA1 in open-access papers (continued):
Sharing a sentence is not in itself a finding about the gene and the disease.
Hereditary breast and ovarian cancer syndrome (233 papers, 1999 to 2026). An autosomal dominant inherited syndrome caused by mutations in the BRCA1 or BRCA2 genes. "Hereditary breast and ovarian cancer syndrome (HBOC) is principally caused by germline mutations in BRCA1 and BRCA2." (PMID 41876608, 2026). "The pathogenic mutations in genes such as MUTYH, FANCD2, NBN, PALB2, and BRCA1 are associated with hereditary breast and ovarian cancer syndrome, an autosomal dominant disorder typically manifesting around age 30 and above." (PMID 41229399, 2025). "Genetic testing has led to a considerable enhancement in the ability to identify individuals at risk of Hereditary Breast and Ovarian Cancer syndrome related to BRCA1/2 pathogenic variants, thus necessitating personalised prevention programs." (PMID 40596937, 2025). "Two of these cases harbored pathogenic variants in the BRCA1 gene thus having a high risk for hereditary breast and ovarian cancer (OMIM #604370)." (PMID 40620702, 2025). "Germline pathogenic or likely pathogenic variants of BRCA1 and BRCA2 (BRCA1/2) are associated with HBOC syndrome, a highly penetrant condition." (PMID 40596937, 2025). "Women who carry a pathogenic variant (mutation) in the BRCA1 gene face a high lifetime risk of developing breast (and ovarian) cancer." (PMID 41440233, 2025). "For instance, the ATM gene is well-known as the third most frequently mutated gene in hereditary breast and ovarian cancer (HBOC) after BRCA1 and BRCA2." (PMID 41022541, 2025). "The large number of cases of HBOC syndrome is caused by the presence of germline mutations in either the BRCA1 or the BRCA2 gene located on chromosome 17q21 and 13q12-13, respectively." (PMID 40648909, 2025). "Based on this mapping, the duplications arose independently but share the same outcome, i.e., a BRCA1 loss-of-function linked to HBOC syndrome." (PMID 38892462, 2024). "BRCA1, frequently mutated in hereditary breast and ovarian cancers (HBOCs), is crucial for maintaining genomic stability, activating DNA damage repair (DDR), mediating ubiquitination, modifying chromatin, and influencing apoptosis and gene regulation." (PMID 38543119, 2024). "Mutations in the BRCA1 gene are a marker for predicting susceptibility to high-risk cancers, particularly hereditary breast and ovarian cancer syndrome (HBOC), fallopian tube, prostate, and colon cancers." (PMID 38543119, 2024). "Pathogenic TE insertions are associated with various hereditary cancers, including hereditary breast and ovarian cancer syndrome (BRCA1, BRCA2, and BARD1); Lynch syndrome (MLH1); and colorectal cancer (APC)." (PMID 39697868, 2024). "HBOC syndrome is a cancer susceptibility syndrome caused by germline mutations in BRCA1 and/or BRCA2 and is inherited in an autosomal dominant manner." (PMID 39590127, 2024). "A total of eleven women with hereditary breast and ovarian cancer (HBOC) (including BRCA1/2 mutation carriers), and Lynch syndrome (including MMR gene mutation carriers) were included." (PMID 38800375, 2024). "In an effort to identify PGVs on other HBOC syndrome causative genes, all selected probands were wildtype for BRCA1/BRCA2 alleles." (PMID 39003386, 2024). "For example, in neurofibromatosis type 1 patients, splicing mutations in NF1 represents the 40% of the amount of causative variants, whereas in hereditary breast/ovarian cancer, splicing aberrations in BRCA1/2 are about 49%." (PMID 39944559, 2024). "A pathogenic variant in BRCA1 (c.181T>G) known to cause a predisposition to inherited breast and ovarian cancer (OMIM 604370) was identified in patient KTWW." (PMID 38102329, 2024).
Hereditary breast and ovarian cancer syndrome (continued). "Recently, molecular analysis revealed that PACC shows a high frequency of the BRCA1/2 mutation and is likely to be considered a cancer associated with hereditary breast and ovarian cancer (HBOC)." (PMID 39188100, 2024). "We previously reported the prevalence of germline variants among Japanese patients with BRCA1/BRCA2-wildtype HBOC syndrome and a strong family history." (PMID 39003386, 2024). "Approximately 30–50% of hereditary breast and ovarian cancer (HBOC) is due to the presence of germline pathogenic variants in the BRCA1 (OMIM 113705) and BRCA2 (OMIM 600185) onco-suppressor genes, which are involved in DNA damage response." (PMID 37958491, 2023). "BRCA1 gene mutations cause familial breast-ovarian cancer-1 (BROVCA1), and BRCA2 gene mutations cause familial breast-ovarian cancer-2 (BROVCA2)." (PMID 36835955, 2023). "Prophylactic interventions are critical for BRCA1/2 mutation carriers to reduce the risks of hereditary breast and ovarian cancer (HBOC)." (PMID 38201529, 2023). "In contrast, in another study on 279 members of families with BRCA1-linked hereditary breast-ovarian cancer, testing appears correlated with a greater number of affected first-degree relatives." (PMID 37723374, 2023). "The most common cause of hereditary breast and ovarian cancers (HBOC) is the presence of mutations in the BRCA1 and BRCA2 genes." (PMID 37685988, 2023). "Each of these four genes is mutated in a hereditary disease/syndrome, which are the hereditary breast and ovarian cancer syndrome (BRCA1), α-gammaglobulinemia (BTK), Fanconi anemia (FANCA), and spastic paraplegia 4 (SPAST)." (PMID 36075911, 2022). "Mutations in the BRCA1 or BRCA2 genes result in the clinical presentation known as hereditary breast and ovarian cancer syndrome." (PMID 35685436, 2022). "Pathogenic germline variants in Breast cancer susceptibility gene 1 (BRCA1) predispose carriers to hereditary breast and ovarian cancer (HBOC)." (PMID 34981296, 2022). "The aim of this study was to assess the prevalence of germline variants in cancer-predisposing genes by either targeted (BRCA1/2) or multigene NGS panel in a high-risk Hereditary Breast and Ovarian Cancer (HBOC) cohort." (PMID 35451682, 2022). "Accurately characterizing BRCA1/2 mutational status, including BRCA1/2 somatic and germline mutations, can guide treatment for patients with these gene alterations and help assess the risk of developing hereditary breast and ovarian cancer (HBOC)." (PMID 36147908, 2022). "The most common cause of hereditary BC is a GPV in BRCA1 or BRCA2 (BRCA1/2) associated with hereditary breast and ovarian cancer (HBOC)." (PMID 35806485, 2022). "Hereditary breast and ovarian cancer syndrome (HBOC) is a hereditary tumor that can be definitively diagnosed by the detection of a germline mutation of the BRCA1 or BRCA2 gene." (PMID 35769138, 2022). "Approximately 5%-10% of breast cancer and 20% of ovarian cancer cases occur due to germline pathogenic variants associated with hereditary breast and ovarian cancer (HBOC) syndrome, most commonly observed in the BRCA-1 and BRCA-2 genes (hereafter BRCA)." (PMID 34114954, 2021). "Hereditary Breast and Ovarian Cancer Syndrome (HBOC) is an autosomal dominantly inherited condition caused by the presence of germline pathogenic variants (PVs) in the BRCA1 and BRCA2 genes." (PMID 34572941, 2021).
Hereditary breast and ovarian cancer syndrome (continued). "Pathogenic variants in the tumor suppressor genes BRCA1 and BRCA2 (BRCA1/2) and other genes, mainly involved in DNA repair, have been linked to high or moderate risks of developing hereditary breast and ovarian cancer (HBOC)." (PMID 34283047, 2021). "We found that ten recurrent BRCA1/2 pathogenic variants account for more than half of the patients with proven HBOC syndrome from Apulia." (PMID 34572941, 2021). "For example, a Singapore study that studied individuals with a personal or FH of familial breast/ovarian cancers (FBOCs) with the BRCA1 c.442-22_442-13del variant, found that this variant was more common in patients of Chinese origin." (PMID 34926254, 2021). "The discovery of hereditary breast-ovarian cancer genes was initially viewed as an advance in preventive medicine, with the focus on timely cancer diagnosis and prophylactic surgery applied to BRCA1/2 mutation carriers." (PMID 34454564, 2021). "For example, hereditary breast and ovarian cancer (HBOC) syndrome is a hereditary syndrome associated with a high risk of breast and ovarian cancer that is caused by pathological alterations of the BRCA1 or BRCA2 gene in germline cells." (PMID 33249514, 2021). "Similar to the effect of BRCA1/2 mutations in hereditary breast and ovarian cancer, BRCA1/2 variants have been shown to be moderately elevated to increase PCa risk across populations." (PMID 34820334, 2021). "Detection of mutations in hereditary breast and ovarian cancer related BRCA1 and BRCA2 genes is an effective method of cancer prevention, early detection, and treatment." (PMID 34490083, 2021). "In the current study, we performed next-generation sequencing analyses on 28 previously known disease-causing genes for HBOC syndrome, focusing on 568 Japanese BRCA1/2 WT index patients with a strong family history." (PMID 32566746, 2020). "Here, we examined the prevalence of germline variants among 568 Japanese patients with BRCA1/2-wildtype HBOC syndrome and a strong family history." (PMID 32566746, 2020). "Hereditary breast and ovarian cancer syndrome (HBOC) is diagnosed when a pathogenic variant is identified in the BRCA1 or BRCA2 (BRCA1/2) genes, which are involved in DNA damage repair." (PMID 33327492, 2020). "An increased melanoma risk has been documented in carriers of germline mutations causing other cancer syndromes, including hereditary breast and ovarian cancer (BRCA1/BRCA2), retinoblastoma (RB1), or xeroderma pigmentosum (XPs)." (PMID 33050356, 2020). "BRCA1/2 variants are prognostic biomarkers for hereditary breast and/or ovarian cancer (HBOC) syndrome and predictive biomarkers for PARP inhibition." (PMID 32486089, 2020). "Up to 25% of women diagnosed with HGSC have germline deleterious mutations in BRCA1 or BRCA2 characteristic of hereditary breast and ovarian cancer syndrome (HBOC), while somatic mutations have been detected in 3–7%." (PMID 33233347, 2020). "The role of germline mutations in the breast-ovarian cancer predisposition genes BRCA1 and BRCA2 in the risk of familial melanoma development is still a matter of debate and the exact melanoma risk increase (if any) in mutation carriers is uncertain." (PMID 33050356, 2020). "To date, there have been several attempts to describe the spectrum of BRCA1/2 germline pathogenic variants in Moroccan patients with HBOC syndrome." (PMID 32778078, 2020). "As regards the typology of cancer associated with HBOC syndrome in the BRCA1 PV carriers, 60% of tumors was represented by female BC, 26% by OC, 10% by both (primary BC and OC) and finally 3% by male BC." (PMID 32380732, 2020).
Hereditary breast and ovarian cancer syndrome (continued). "This study highlights Japanese-associated germline mutations among patients with BRCA1/2 wildtype HBOC syndrome and a strong family history, and provides evidence for the medical care of this high-risk population." (PMID 32566746, 2020). "We evaluate the usefulness of the target detection of 9–12 del BRCA1 as the first molecular diagnostic strategy in patients with Hereditary Breast and Ovarian Cancer (HBOC)." (PMID 31545835, 2019). "Hereditary Breast and Ovarian Cancer (HBOC) syndrome is an inherited disorder in which specific genetic mutations (principally BRCA1 and BRCA2 genes) are associated with an increased risk for Breast (BC) and Ovarian Cancer (OC)." (PMID 30841601, 2019). "Between 5 and 10% of all BC and 13–15% of OC are hereditary and approximately 25% are associated with the Hereditary breast/ovarian cancer (HBOC) syndrome, caused by abnormalities in the DNA repair genes BRCA1 and BRCA2." (PMID 31771539, 2019). "Cancer predisposition in hereditary breast and ovarian cancer (HBOC) syndrome is caused by pathogenic germline variants in the BRCA1/2 genes (germline BRCA variants) and is inherited in an autosomal dominant pattern." (PMID 31346352, 2019). "The risk of serous PPC increases in patients with hereditary breast and ovarian cancer syndrome or BRCA1 or BRCA2 mutations." (PMID 31823088, 2019). "For example, the breast cancer type I susceptibility gene (BRCA1), a prominent tumor suppressor gene whose mutation predisposes women to hereditary breast-ovarian cancers, has been reported to bear 84% sequence homology in dogs and humans." (PMID 31508437, 2019). "BRCA1/2 mutations are significant risk factors for hereditary breast and ovarian cancer (HBOC), its mutation frequency in HBOC of Chinese ethnicity is around 9%, in which nearly half are recurrent mutations." (PMID 29487695, 2018). "Hereditary breast and ovarian cancer syndrome (HBOC) is most frequently caused by mutations in BRCA1 or BRCA2 (in short, BRCA) genes." (PMID 29659587, 2018). "Deleterious variants in the tumour suppressor BRCA1 are known to cause hereditary breast and ovarian cancer syndrome (HBOC)." (PMID 30458859, 2018). "To date, much of the research on the clinical management of hereditary breast and ovarian cancer syndrome has focused on carriers of germline BRCA1 or BRCA2 mutations." (PMID 30174725, 2018). "BRCA1 was the first gene discovered to be associated with hereditary breast and ovarian cancer syndrome." (PMID 30174725, 2018). "In conclusion comprehensive BRCA1/2 testing in AJ high risk breast ovarian cancer cases adds valuable clinically relevant information in a subset of cases estimated up to 7% and is therefore recommended." (PMID 30186769, 2018). "Hereditary breast and ovarian cancer syndrome (HBOC) is an inherited condition that is most often associated with mutations in the BRCA1 and BRCA2 (BRCA1/2) genes." (PMID 30103738, 2018). "Hereditary breast and ovarian cancer syndrome (HBOC) is an autosomal dominant inherited cancer susceptibility disorder caused by deleterious germline mutations in BRCA1 or BRCA2 (BRCA1/2)." (PMID 29176636, 2018). "Hereditary breast and ovarian cancer syndrome most frequently occur through inheritance of mutations in the BRCA1 and BRCA2 genes." (PMID 29659587, 2018). "We first evaluated the frequency of pathogenic variants in BRCA1/2, genes that are known to cause hereditary breast and ovarian cancer (HBOC)." (PMID 28166811, 2017). "Germline variants within BRCA1 or BRCA2 genes account for approximately 25% of familial aggregations of breast-ovarian cancers." (PMID 29021870, 2017). "Germline variants within BRCA1 or BRCA2 genes account for approximately 25% of familial aggregations of breast-ovarian cancer that are clinically manifested as hereditary breast and ovarian cancer syndrome (HBOC)." (PMID 29021870, 2017).
Hereditary breast and ovarian cancer syndrome (continued). "Hereditary breast and ovarian cancer syndrome, caused by a germline pathogenic variant in the BRCA1 or BRCA2 (BRCA1/2) genes, is characterized by an increased risk for breast, ovarian, pancreatic and other cancers." (PMID 27375968, 2016). "Germ line mutations in BRCA1 and BRCA2 (BRCA1/2) and other susceptibility genes have been identified as genetic causes of hereditary breast and ovarian cancer (HBOC)." (PMID 24884479, 2014). "Hereditary breast and ovarian cancer (HBOC) reveals as a monogenic predisposition of offspring features autosomal dominant inheritance due to constitutional mutations in the BRCA1 gene." (PMID 23941236, 2013). "The number of BRCA1 mutations exceeds the one of probands diagnosed by clinical criteria for hereditary breast-ovarian cancer, group 1." (PMID 21034437, 2010). "In the present study, a germline pathogenic mutation in either BRCA1 or BRCA2 was identified in 10% of screened breast-ovarian cancer families (BRCA1 mutations were detected in about 3% of cases, while BRCA2 mutations were identified in about 7% of families)." (PMID 19619314, 2009). "Genomic DNA from 348 probands of breast-ovarian cancer families was screened for germline mutations in BRCA1 and BRCA2 genes." (PMID 19619314, 2009). "Several genes conferring susceptibility to breast and ovarian cancer, notably BRCA1 and BRCA2, have been identified." (PMID 15381934, 2004). "We also typed 124 affected and 276 unaffected female carriers with known deleterious BRCA1 or BRCA2 germline mutation from high-risk breast-ovarian cancer families." (PMID 10487631, 1999). "However, women with HBOC syndrome, on average, experience menopause earlier than usual, and based on genome-wide association studies, it is known that being a carrier of BRCA1 or BRCA2 gene mutation is related with increased ovarian aging." (PMID 39061239, 2024). "Melanoma risk is also thought to be increased in cancer predisposition syndromes including Cowden syndrome, Li-Fraumeni syndrome, and hereditary breast and ovarian cancer syndrome, caused by pathogenic variants in phosphatase and tensin homolog, tumor protein 53, and BRCA1 and BRCA2, respectively." (PMID 39188332, 2024). "As suggested by Pritchard (2019) the terminology of the syndrome itself—BRCA1- and BRCA2-associated Hereditary Breast and Ovarian Cancer syndrome–is considered misleading and should be changed because it induces the false belief that BRCA1/2 mutations are "women’s business" only." (PMID 35303741, 2022). "Discoveries in observational studies and family studies led to the determination of genetic factors involved in EOC risk, notably those associated with the so-called hereditary breast and ovarian cancer (HBOC) syndrome caused by germline mutations in BRCA1 or BRCA2 (BRCA1/2)." (PMID 35267439, 2022). "Genetic testing should also be considered for all patients with a diagnosis of gastric neoplasia and a family history compatible with Lynch syndrome, FAP, Peutz–Jeghers, Li–Fraumeni, juvenile polyposis, hereditary breast and ovarian cancer syndrome (germline mutations in BRCA1 or BRCA2)." (PMID 33804024, 2021). "Therefore, BRCA1/2 genetic analysis has become a fundamental concern of doctors and families with a high risk of HBOC syndrome." (PMID 32778078, 2020). "BRCA1 or BRCA2 mutations may be suspected in those families with multiple breast-ovarian cancer cases, especially when they are diagnosed at early age." (PMID 28670351, 2017). "HBOC syndrome is caused mainly by germline mutations in BRCA1/2 genes." (PMID 28670351, 2017). "The presence of germline mutations in cancer susceptibility genes other than BRCA1/2 may also lead to the development of hereditary breast/ovarian cancers." (PMID 25948282, 2015). "Interestingly, in three unrelated families from the South and Middle Sardinia we identified carriers of the BRCA1 c.916_917delTT mutation that has been reported in breast-ovarian cancer families from South Italy." (PMID 19619314, 2009).